LEP (leptin)
Diseases named in the same sentence as LEP in open-access papers (continued):
Sharing a sentence is not in itself a finding about the gene and the disease.
periodontitis (continued). "Current studies have shown that there is a close relationship between leptin and periodontitis." (PMID 38111655, 2023). "In patients with periodontitis, leptin levels in GCF increased after root planing alone and root planing with local administration of tetracycline, with the latter having a greater increase, which gradually reverted to a normal level (Meharwade, Gayathri & Mehta, 2014)." (PMID 38111655, 2023). "Leptin may be involved in periodontitis development, whereas periodontitis may affect the pathological process of systemic diseases by influencing leptin." (PMID 38111655, 2023). "A previous study indicated that exogenous infusion of leptin could aggravate periodontitis by activating macrophages." (PMID 37488474, 2023). "The divergent results in the studies discussed earlier suggest that various factors could contribute to alterations in serum leptin levels during the progression of periodontitis." (PMID 38111655, 2023). "Of note, periodontitis increases the serum leptin levels, may due to the altered oral microbiome disorder in patients with periodontitis." (PMID 38111655, 2023). "Thus, additional research is needed to comprehensively explore leptin’s specific characteristics, its relationship with periodontitis, and its effects on periodontal tissue metabolism." (PMID 38111655, 2023). "Here, we summarize the relationship between leptin and periodontitis, comprehensively exploring the possible mechanisms by which leptin may affect periodontitis, either positively or negatively, and analyzing potential causal relationships." (PMID 38111655, 2023). "Here, we reviewed current progress on leptin and periodontitis." (PMID 38111655, 2023). "The elevated leptin levels in obese individuals could promote inflammatory cytokine activation in the body, disrupting the oral microbiota and exacerbating periodontitis development." (PMID 38111655, 2023). "Furthermore, leptin can influence the pathological process of periodontitis by regulating the immune system, the level of inflammatory factor, bone metabolism, and extracellular matrix of periodontal tissues." (PMID 38111655, 2023). "Conversely, periodontitis can impact diabetes by influencing leptin." (PMID 38111655, 2023). "Moreover, they reported that leptin promoted the progression of periodontitis via the polarization of inflammatory M1 macrophages." (PMID 36979821, 2023). "The results of the present study indicate that leptin released under systemic conditions may dysregulate the innate immunity in the gingival epithelium and lamina propria, and then lead to the chronic periodontitis." (PMID 33967621, 2021). "Previous studies 4-6 have shown that leptin may be involved in the development of chronic periodontitis." (PMID 33967621, 2021). "Few studies have investigated the relationship between leptin and chronic periodontitis." (PMID 33967621, 2021). "Besides this, nine clinical trials detecting the serum levels of leptin and adiponectin in patients with periodontitis before and after periodontal treatments were included." (PMID 28662701, 2017). "Previous studies have reported increased serum levels of leptin in patients with periodontitis." (PMID 26330934, 2015). "Interestingly, the downregulation of leptin and adiponectin was paralleled by a significant upregulation of their receptors in gingival biopsies from periodontitis subjects." (PMID 24707118, 2014). "Although previous studies have evaluated salivary levels of leptin, calprotectin, and adiponectin in systemic and periodontal diseases, those comparing the levels of these biomarkers across periodontal health, gingivitis, and periodontitis within the same population remain limited." (PMID 41300847, 2025). "However, the precise mechanisms by which leptin participates in the pathogenesis of periodontitis remain unclear." (PMID 41154857, 2025). "It has also been observed that the presence of periodontitis may raise plasma leptin levels." (PMID 41154857, 2025).
periodontitis (continued). "Furthermore, recent clinical studies have demonstrated that non-surgical periodontal treatment can improve clinical parameters (clinical attachment levels, plaque index, probing depth, and so on,) in periodontitis patients and significantly increase leptin levels in GCF." (PMID 38111655, 2023). "However, the specific mechanism by which leptin participates in the pathogenesis of periodontitis, its interaction with inflammatory factors, and its potential immune function in periodontitis remain unclear." (PMID 38111655, 2023). "However, a recent clinical comparative study demonstrated that patients with periodontitis in high-altitude areas had lower serum leptin levels than a group of 50 healthy controls and that the serum leptin levels were negatively correlated with probing depth and clinical attachment loss." (PMID 38111655, 2023). "Periodontitis‐related systemic inflammation may contribute to insulin resistance through elevated blood levels of adipocytokines, such as tumor necrosis factor alpha, IL‐6, and leptin, which inhibit the insulin receptor and its downstream signaling." (PMID 34463983, 2021). "Importantly, the mechanism of action of leptin in the development of chronic periodontitis was also explored, which may help us to better understand, and therefore treat, chronic periodontitis in the future." (PMID 33967621, 2021). "Therefore, the cause–effect relationship between periodontitis and serum levels of leptin and adiponectin was rarely presented, and the effect of periodontal treatment on serum levels of leptin and adiponectin was not perfectly elucidated." (PMID 28662701, 2017). "Indeed, the data of the present study do not show any association between CRP, IL-6, leptin or adiponectin with periodontitis in morbidly obese patients." (PMID 23526947, 2013). "Four weeks after treatment, the correlations between TNF-α and leptin, adiponectin, resistin, FFA, the gingival bleeding index, and periodontitis grade were significantly greater (P < 0.05)." (PMID 41244040, 2025). "Using a Multivariate logistic regression model, periodontitis correlates to BMI, WHR, serum levels of triglyceride, total cholesterol, low density lipoprotein, and adipokines such as visfatin, leptin, and resistin." (PMID 37231396, 2023). "This study aimed to investigate the expression of leptin, OPG, and RANKL in human gingival tissues to elucidate the role of leptin in chronic periodontitis." (PMID 33967621, 2021). "The objective of this study was to assess the serum levels of adiponectin, leptin and TNF-α of periodontally healthy normal weight (NW) patients, NW patients with chronic periodontitis (CP), periodontally healthy obese patients and obese patients with CP." (PMID 26330934, 2015). "By contrast, leptin levels are decreased in GCF and gingival tissues in periodontitis patients, as compared to periodontally healthy individuals." (PMID 25136363, 2014). "For example, certain studies have reported decreased leptin levels in the gingival fluid and saliva of patients with periodontitis, along with a negative correlation between gingival fluid leptin levels and disease activity or progression." (PMID 41154857, 2025). "Data from the literature indicate that patients with both DM and periodontitis, compared to those without DM, have significantly elevated levels of leptin and significantly reduced levels of adiponectin." (PMID 40243433, 2025). "Unlike leptin and calprotectin, the anti-inflammatory adipokine adiponectin was highest in the healthy group and significantly lower in the periodontitis group." (PMID 41300847, 2025). "The findings revealed a negative correlation between the degree of periodontitis and leptin levels in the gingival tissue, saliva, and GCF." (PMID 38111655, 2023). "Next, we wanted to test the effect of leptin on the proinflammatory reaction of macrophages without and with additional LPS from Porphyromonas gingivalis to mimic inflammation occurring during periodontitis." (PMID 36142638, 2022).
periodontitis (continued). "Patients with Owt or Ob had higher plasma levels of CRP and leptin, but lower levels of adiponectin, compared with normal weight (Nwt) participants, irrespective of periodontitis status." (PMID 33603787, 2021). "Patients in the Owt/Ob group had significantly higher leptin levels than patients in the Nwt group, irrespective of periodontitis status (p < 0.03)." (PMID 33603787, 2021). "NSPT reduces serum levels of CRP and leptin while enhancing serum levels of adiponectin, in Thai patients with Owt or Ob, irrespective of periodontitis severity." (PMID 33603787, 2021). "Therefore, this study aimed to investigate the possible role of leptin by examining its relationship with OPG and RANKL in human gingival tissues obtained from patients with chronic periodontitis." (PMID 33967621, 2021). "In systemically healthy patients with periodontitis, serum levels of leptin and adiponectin do not significantly change after periodontal treatment." (PMID 28662701, 2017). "In this light, it was concluded that serum levels of leptin and adiponectin did not change after periodontal treatment in systemically healthy patients with periodontitis." (PMID 28662701, 2017). "The overall and subgroup analyses showed no significant change in the serum levels of leptin in patients with periodontitis after periodontal treatment." (PMID 28662701, 2017). "In the L2 model, the overall and subgroup analyses showed no significant change in serum levels of leptin in patients with periodontitis after periodontal treatment." (PMID 28662701, 2017). "In systemically healthy patients with periodontitis, serum levels of leptin and adiponectin did not significantly change after periodontal treatment." (PMID 28662701, 2017). "Thus, the objective of this study was to assess the serum levels of adiponectin, leptin and TNF-α of periodontally healthy (PH) normal weight (NW) subjects, NW subjects with chronic periodontitis (CP), PH obese subjects and obese subjects with CP." (PMID 26330934, 2015). "The null hypothesis (H0) stated that salivary leptin, adiponectin, and calprotectin levels do not differ among individuals with periodontal health, gingivitis, and periodontitis." (PMID 41300847, 2025). "The null hypothesis stating that salivary leptin, adiponectin, and calprotectin levels do not differ among individuals with periodontal health, gingivitis, and periodontitis was rejected, as significant intergroup differences were observed for all biomarkers." (PMID 41300847, 2025). "However, a 2017 meta-analysis found that serum leptin levels in systemically healthy periodontitis patients did not change after periodontal treatment." (PMID 38111655, 2023). "Furthermore, the mean serum leptin levels at baseline were significantly higher in patients with Owt or Ob than in Nwt patients, irrespective of periodontitis condition." (PMID 33603787, 2021). "Our results strongly suggest that leptin may be involved in the development of chronic periodontitis by modulating the OPG/RANKL system; however, further studies are required to fully explore the specific mechanisms through which leptin regulates chronic periodontitis." (PMID 33967621, 2021). "Although only PDL cells were used in our experiments, it can be speculated that the increased serum leptin levels observed in periodontitis do not result from an enhanced local production of leptin in the periodontium." (PMID 25136363, 2014). "Taken together, our study shows for the first time that inflammatory, microbial, and biomechanical signals can inhibit the expression of leptin and its receptor in PDL cells, which may explain, at least in part, the reduced GCF leptin levels found in periodontitis and orthodontic patients." (PMID 25136363, 2014).
periodontitis (continued). "Furthermore, experimental periodontitis exacerbates inflammation not only by increasing the stromal vascular fraction (SVF) in AT to promote pro-inflammatory cytokine (TNF-α and IL-6) secretion, but also by altering circulating levels of adipokines such as resistin, adiponectin, and leptin." (PMID 41246338, 2025). "A study conducted in Thailand revealed that non-surgical periodontal treatment can reduce serum leptin and C-reactive protein (CRP) levels in periodontitis patients." (PMID 38111655, 2023). "Compared with baseline, the mean leptin levels at 6 months after NSPT remained significantly lower among patients in the Owt/Ob group, irrespective of periodontitis status (p = 0.01 and p = 0.009)." (PMID 33603787, 2021). "NSPT reduces serum levels of leptin and CRP and enhances serum levels of adiponectin in Thai patients with Owt/Ob, irrespective of periodontitis severity." (PMID 33603787, 2021). "Notably, the levels of serum leptin were significantly reduced at 3 and 6 months after NSPT, especially in patients with Owt or Ob, irrespective of periodontitis status." (PMID 33603787, 2021). "Compared with baseline, the mean leptin levels at 3 months after NSPT were significantly lower among patients in the Owt/Ob group, irrespective of periodontitis status, as well as among patients in the Nwt with SP group (p = 0.01, p < 0.001, and p = 0.01, respectively)." (PMID 33603787, 2021).
lung cancer (47 papers, 2010 to 2025). A malignant neoplasm involving the lung. "Studies have shown that in lung cancer patients, high plasma leptin levels associated with fructose concentration improve the antitumor response of CD8+ T cells, revealing the potential application of the fructose-leptin axis in cancer therapy." (PMID 40520908, 2025). "Leptin has also been implicated in promoting immune evasion in lung cancer by upregulating proinflammatory cytokines." (PMID 40013137, 2025). "Leptin is classically described as regulator of food intake and energy expenditure, where elevated circulating levels of leptin are associated with adipose tissue inflammation and implicated in breast, colon, prostate, pancreas, ovary, and lung cancers." (PMID 35164764, 2022). "In cell culture models, lung cancer cell lines A549 and H460 were used to investigate the effect of leptin on cell viability and its underlying mechanism of action." (PMID 33708630, 2021). "All 14 eligible case–control studies (773 cases and 594 controls) were included in the meta-analysis to investigate the association between serum leptin concentrations and lung cancer." (PMID 28160559, 2017). "The results indicated evidence for a significant association between expression levels of leptin protein in tissue and lung cancer (OR=7.35, 95%CI=5.21–10.39, P<0.001)." (PMID 28160559, 2017). "Further, there was evidence of a significant association between expression levels of leptin protein in tissue and lung cancer (OR=7.35, P<0.001)." (PMID 28160559, 2017). "Among them, fourteen included articles regarding the association between the serum leptin levels and lung cancer, and seven included articles about the association between the leptin expression levels in tissue and lung cancer." (PMID 28160559, 2017). "Moreover, leptin seems to decrease the development of Tregs, which are associated with poorer outcomes and lower survival rates in various cancers, including lung cancer." (PMID 38534454, 2024). "Despite the few studies linking leptin to the progression of lung cancer, it has been reported that the polymorphism of the leptin gene LEP-2548 G/A increases the susceptibility to the development of non-small-cell lung cancer (NSCLC), which represents 75–80% of lung cancer." (PMID 33334030, 2020). "Therefore, we carried out a most recent meta-analysis to accurately investigate the association between leptin and the risk of lung cancer, and to further assess the role of leptin in lung cancer." (PMID 28160559, 2017). "However, a subgroup analysis in high-study quality group found a weak association between serum leptin concentrations and lung cancer in Chinese (SMD=0.77, P=0.035)." (PMID 28160559, 2017). "In addition, increased adiponectin and leptin production in visceral adipose tissue may be associated with improved OS in lung cancer." (PMID 37724690, 2023). "BMI has been reported with a linear association with adipokine or leptin, which played a critical role in a number of pathways such as inflammatory response, energy regulation, and tumorigenesis, which may associate with the risk of lung cancer." (PMID 35102723, 2022). "Therefore, we analyzed the role of serum leptin in lung cancer patients with weight loss." (PMID 28160559, 2017). "In this review, we summarized the roles of sex-specific bioactive molecules (estrogens, progesterone, testosterone, FSH, LH, prolactin, leptin, activin, and inhibin) in the immune response to lung cancer and immunotherapy effectiveness." (PMID 41463203, 2025). "This evidence confirms that leptin enhances lung cancer cell growth and migration through suppressing apoptosis." (PMID 38571500, 2024). "In vitro studies on lung cancer bone metastasis have shown that leptin promotes metastasis of the A549 human lung cancer cell line through a TGF-β-dependent induction of EMT." (PMID 38571500, 2024).